U3 (Small nucleolar RNA U3 )
Synonyms: LOC124902100
Gene: Small nucleolar RNA gene on chromosome 8 (43,378,297 to 43,378,510, forward strand). Ensembl gene ENSG00000201329.
Gene Ontology:
Biological process: RNA processing
Cellular component: nucleolus
Homologues: Orthologues: chimpanzee U3 (93% identical), pig U3 (32% identical). Paralogues in human: SNORD3P1 (79% identical), U3 (78% identical), SNORD3E (77% identical), U3 (77% identical), SNORD3D (77% identical), U3 (76% identical), SNORD3H (75% identical), U3 (75% identical), SNORD3G (75% identical), U3 (74% identical), U3 (73% identical), U3 (72% identical), and 12 more.